SCARB2 (scavenger receptor class B member 2)
Description:
Acts as a lysosomal receptor for glucosylceramidase (GBA1) targeting. (Microbial infection) Acts as a receptor for enterovirus 71.
Synonyms: LGP85; CD36L2; LIMPII; HLGP85; SR-BII; LIMP-2; AMRF; EPM4
Tractability: Small molecule: a structure with a bound ligand is known. Antibody: its Gene Ontology location is reachable by antibodies, with high confidence; UniProt predicts a signal peptide or a membrane-spanning region. PROTAC: its protein half-life has been measured.
Gene: Protein-coding gene on chromosome 4 (76,158,737 to 76,234,536, reverse strand). Ensembl gene ENSG00000138760.
Subcellular location: Lysosome membrane
Subcellular location (Human Protein Atlas): Cytosol
Pathways (Reactome):
Vesicle-mediated transport: Cargo recognition for clathrin-mediated endocytosis; Clathrin-mediated endocytosis
Gene Ontology:
Molecular function: cargo receptor activity; enzyme binding; protein binding; protein homodimerization activity; cholesterol binding; phosphatidylcholine binding; phosphatidylserine binding; scavenger receptor activity; transmembrane signaling receptor activity; protein-folding chaperone binding
Biological process: protein targeting to lysosome; regulation of carbohydrate catabolic process; aminophospholipid transport; glycolipid catabolic process; positive regulation of neuron projection development; receptor-mediated endocytosis; regulation of endosome organization; regulation of glucosylceramide catabolic process; regulation of lysosome organization; autophagy
Cellular component: extracellular exosome; focal adhesion; lysosomal membrane; membrane; clathrin-coated endocytic vesicle membrane; endocytic vesicle membrane; endoplasmic reticulum membrane; endosome membrane; Golgi membrane; late endosome membrane; lysosomal lumen; plasma membrane; lysosome
Genetic constraint (gnomAD): Loss-of-function variants: 25 observed, 51.12 expected, observed/expected ratio (o/e) 0.49, 90% interval 0.35 to 0.68. The upper end of that interval is the gene's LOEUF score, 0.68, which puts it in group 2 of 6, group 1 being the genes least tolerant of losing a copy. Missense variants: 461 observed, 568.05 expected, observed/expected ratio (o/e) 0.81, 90% interval 0.75 to 0.88. Synonymous variants: 186 observed, 208.27 expected, observed/expected ratio (o/e) 0.89, 90% interval 0.79 to 1.01.
Gene-disease validity (ClinGen):
ClinGen rates the evidence that SCARB2 causes each of these diseases.
progressive myoclonus epilepsy (autosomal recessive): Definitive. A rare group of disorders characterized by the development of myoclonic and tonic-clonic epileptic seizures associated with progressive degeneration of the nervous system.
Homologues: Orthologues: chimpanzee SCARB2 (99% identical), macaque SCARB2 (98% identical), rabbit SCARB2 (90% identical), dog SCARB2 (86% identical), pig SCARB2 (86% identical), mouse Scarb2 (86% identical), rat Scarb2 (84% identical), guinea pig SCARB2 (81% identical), tropical clawed frog scarb2 (54% identical), Caenorhabditis elegans scav-1 (30% identical), zebrafish scarb2c (29% identical), Caenorhabditis elegans scav-2 (28% identical), and 1 more. Paralogues in human: SCARB1 (32% identical), CD36 (32% identical).
Diseases named in the same sentence as SCARB2 in open-access papers:
SCARB2 is named in the same sentence as 106 diseases in open-access papers, as found by Europe PMC text mining. Sharing a sentence is not in itself a finding about the gene and the disease. The quoted sentences say what the papers report.
Gaucher disease (14 papers, 2014 to 2026). Gaucher disease (GD) is a lysosomal storage disorder encompassing three main forms (types 1, 2 and 3), a fetal form and a variant with cardiac involvement (Gaucher disease - ophthalmoplegia - cardiovascular calcification or Gaucher-like disease). "Deficiency in SCARB2 is related to both Gaucher disease (GD) and Parkinson’s disease (PD), which are both neurodegenerative-related diseases." (PMID 37739936, 2023). "Deficiency in SCARB2 has been found to be associated with Gaucher disease (GD) and Parkinson’s disease (PD), which are both neurodegenerative diseases." (PMID 35955761, 2022). "Deficiency in scavenger receptor class B, member 2 (SCARB2) is related to both Gaucher disease (GD) and Parkinson’s disease (PD), which are both neurodegenerative-related diseases without cure." (PMID 35955761, 2022). "Scarb2 acts as the mannose-6-phosphate-independent trafficking receptor for β-glucocerebrosidase (β-GCase), a lysosomal enzyme that is deficient in most cases of Gaucher disease (GD)." (PMID 38635907, 2024). "Scavenger receptor class B, member 2 (SCARB2) is linked to Gaucher disease and Parkinson’s disease." (PMID 38635907, 2024). "In Gaucher disease, variants in the SCARB2 or PSAP may modulate neurological involvement." (PMID 41567994, 2026). "Transcripts for the lysosomal proteins hexosaminidase subunit A, aspartyl glucosaminidase, cathepsin K, SCARB2/LIMP2 and iduronidase alpha all rose significantly in control, Gaucher disease and Parkinson’s disease with GBA mutation cells after ambroxol treatment." (PMID 24574503, 2014). "AMRF is caused by mutations in SCARB2, which encodes LIMP-2, a lysosomal integral membrane protein with various functions including receptor recognition of phospholipids and viruses, cholesterol transport, and the transport of β- GBA (mutated in Gaucher disease) to the lysosome." (PMID 32435656, 2020). "SCARB2 pathogenic variants have not been only implicated in AMRF but also in the pathogenesis of Parkinson’s disease (PD) and Gaucher disease (GD), suggesting the importance of genetic and functional studies in the clinical and the diagnostic settings." (PMID 35346091, 2022). "Several of the proteins that we found to be differentially expressed/abundant in Fabry CMs or in the extracellular space have known roles in other LSDs (including Gaucher disease, SCARB2/LIMP-2 and GBA; Krabbe disease, GALC; and ceroid lipofuscinosis, CTSF), but had never been implicated in FD." (PMID 31378672, 2019).
Parkinson disease (14 papers, 2014 to 2025). A progressive degenerative disorder of the central nervous system characterized by loss of dopamine producing neurons in the substantia nigra and the presence of Lewy bodies in the substantia nigra and locus coeruleus. "Differential gene expression of SCARB2 has been found to be significantly associated with PTSD, and genetic variants within the SCARB2 gene have been associated with Parkinson’s disease in several genetic studies." (PMID 36631443, 2023). "A 2011 Web-based Genome-wide Association (GWA) study found that a nucleotide polymorphism rs6812193 close to SCARB2 was significantly associated with Parkinson’s disease (PD) in people of European ancestry." (PMID 34193186, 2021). "Additionally, it remains unclear whether known Gaucher modifiers like prosaposin (PSAP) or LIMP2 (SCARB2) also play a role in patients with GBA1-associated parkinsonism." (PMID 31464647, 2019). "Previously, the SCARB2/FAM47E locus has also been implicated with Parkinson disease (PD)." (PMID 34935119, 2022).
action myoclonus-renal failure syndrome (11 papers, 2011 to 2023). Action myoclonus-renal failure syndrome (AMRF) is a rare epilepsy syndrome characterized by progressive myoclonus epilepsy in association with primary glomerular disease. "Homozygous mutations in the scavenger receptor class B member 2 (SCARB2) gene cause action myoclonus-renal failure syndrome (AMRF), which is an autosomal recessive progressive myoclonic epilepsy, and are associated with significantly reduced GCase activity in patients." (PMID 32375870, 2020). "Mutations in the lysosomal membrane protein human scavenger receptor class B, member 2 (SCARB2), have recently been found to cause action myoclonus renal failure syndrome (AMRF) in humans, which is characterized by collapsing FSGS and progressive myoclonic epilepsy." (PMID 22693670, 2012). "Action myoclonus-renal failure syndrome (AMRF) is a rare, recessively inherited form of progressive myoclonus epilepsy (PME) caused by mutations in the SCARB2 gene and associated with end-stage renal failure." (PMID 33343627, 2020). "Thus, mutations in SCARB2 (the gene encoding LIMP-2) often lead to a certain phenotypic spectrum of GD, such as a rare form of progressive myoclonic epilepsy (PME) often associated with action myoclonus-renal failure syndrome (AMRF)." (PMID 37111358, 2023).
progressive myoclonus epilepsy (10 papers, 2011 to 2024). "Deficiency in the SCARB2 gene causes progressive myoclonus epilepsy (PME), a rare group of inherited neurodegenerative diseases characterized by myoclonus." (PMID 38635907, 2024). "SCARB2 has also been confirmed as the causative gene of the progressive myoclonic epilepsies (PMEs)." (PMID 35955761, 2022). "Genetically, deficiency of SCARB2 is a risk factor in GD and Parkinson’s disease (PD), while complete loss of function of SCARB2 underlies severe progressive myoclonic epilepsy (PME-4)." (PMID 38635907, 2024). "Biallelic variants in SCARB2 cause progressive myoclonic epilepsy with or without renal failure." (PMID 39711693, 2024). "Homozygous and compound heterozygous mutations of SCARB2 have been identified in patients who had only progressive myoclonus epilepsy (PME) but no renal failure (RF)." (PMID 22032306, 2011). "However, mutations in SCARB2 might account for unsolved cases of progressive myoclonus epilepsy (PME) without renal impairment, especially those resembling Unverricht-Lundborg disease (ULD)." (PMID 21904677, 2011).
viral infection (10 papers, 2012 to 2025). "Both viral infection and replication was well supported in 3T3-SCARB2 and RD cells, while SCARB2-independent EV71 susceptibility was observed in Vero cells." (PMID 22272359, 2012). "To evaluate the functions of PSGL-1 and SCARB2 in EV-A71 interaction with Jurkat cells, we examined the effect of anti-PSGL-1 mAb or anti-SCARB2 pAb on viral infection." (PMID 38359079, 2024). "Further, using PSGL-1 and SCARB2 knockout cells, we found that although both PSGL-1 and SCARB2 are essential for virus infection of Jurkat cells, virus attachment to these cells requires only PSGL-1." (PMID 38359079, 2024). "Targeting SCARB2-virus binding is promised to play an important role in restricting viral infection and spread." (PMID 35359978, 2022). "EV71 binds to SCARB2 through a canyon of VP1 around residue Gln-172 for virus infection, and the entire exon 4 of SCARB2 is responsible for the interaction with the VP1 protein of EV71." (PMID 24602216, 2014). "Notably, SCARB2 expression in neurons and epithelial cells highlights its role in viral infection and subsequent neurological pathogenesis." (PMID 40006936, 2025). "TMEM106A specifically blocks SCARB2-mediated viral infection." (PMID 35359978, 2022). "Thus, our data indicated that TMEM106A blocks SCARB2-dependent viral infection." (PMID 35359978, 2022). "Studies have identified human scavenger receptor class B member 2 (hSCARB2) as a candidate cellular receptor for both CVA16 and EV71, playing a critical role in the early stages of viral infection." (PMID 40143350, 2025). "SCARB2 has been identified as a functional receptor for CVA16 entry into host cells and plays a key role in supporting viral infection." (PMID 40143350, 2025). "Overall, the results suggested that although SCARB2 was crucial for virus infection, it was nonessential for cell attachment." (PMID 34583708, 2021). "Interestingly, the scavenger receptor class B member 2 (SCARB2), which is the most significant elevated plasma protein in the infected cohort, is reported as the cellular receptor for viral infection and responsible for viral entry." (PMID 34844191, 2021). "SCARB2 or PSGL-1 receptor binding is the first step in the development of viral infections, and viral factors (e.g., 5′ UTR, VP1, 3C, 3D, 3′ UTR), host factors and environments (e.g., ITAFs, type I IFN) are also involved in viral infections." (PMID 24602216, 2014). "Only SCARB2-expressing cells showed a decrease of viral infection, not PSGL1-expressing cells." (PMID 35359978, 2022). "Combined approaches measuring viral infection, gene expression, and protein interactions uncovered that TMEM106A is required for optimal IFN-mediated viral inhibition and interferes with EV-A71 binding to host cells on the receptor scavenger receptor class B member 2 (SCARB2)." (PMID 35359978, 2022).
Ataxia (7 papers, 2014 to 2024). Ataxia refers to impaired coordination of voluntary muscle movement. "Pathogenic variants of the SCARB2 gene have been linked to symptoms such as muscle spasm and ataxia in patients; however, the regulatory mechanism of SCARB2 in skeletal muscle growth and development deserves further verification." (PMID 39253524, 2024). "We describe the case of a 29-year-old woman with progressive disabling myoclonus associated with dysarthria and ataxia who was found to have a novel homozygous frameshift mutation in the SCARB2 gene." (PMID 33343627, 2020). "Scavenger receptor B2 (SCARB2) is expressed in human neurons and glial cells and EV-A71 infection of a transgenic mouse model expressing human SCARB2 caused ataxia, paralysis and death of the animals." (PMID 32328043, 2020). "EV71 infection in MAF transgenic mice expressing the human SCARB2 gene leads to ataxia, paralysis, and death in animal experiments." (PMID 37078358, 2023). "In the human CNS, SCARB2 is expressed on neurons and glial cells, and a transgenic mouse model expressing human SCARB2 has exhibited susceptibility to EV71 infection and the development of ataxia, paralysis and death." (PMID 30075025, 2018).
Progressive myoclonic epilepsy (7 papers, 2011 to 2024). "Thus, our findings are not in line with a recent report of high frequency of homozygous or compound heterozygote SCARB2 mutations in patients with isolated PME (clinically resembling Unverricht-Lundborg disease but being negative for CSTB mutations)." (PMID 22032306, 2011).
glioma (4 papers, 2023 to 2025). A benign or malignant brain and spinal cord tumor that arises from glial cells (astrocytes, oligodendrocytes, ependymal cells). "SCARB2 mRNA expression was highly expressed in the glioma cases with IDH mutation and 1p/19q codeletion (p < 0.001)." (PMID 41210942, 2025). "Our study demonstrated that SCARB2 levels were upregulated in glioma tissues and associated with glioma WHO grade." (PMID 41210942, 2025). "Using bioinformatics and in vitro experiments, this research seeks to identify proteins associated with SCARB2 and explores the regulatory pathways involved in glioma, offering important insights into its molecular mechanisms and novel therapeutic approaches for glioma treatment." (PMID 41210942, 2025). "In contrast, a substantial proportion of high-grade glioma samples exhibited moderate to high-intensity staining for SCARB2." (PMID 41210942, 2025). "SCARB2 exhibited higher expression levels in glioma tissues (both GBM and LGG) in comparison with brain tissues (p < 0.05)." (PMID 41210942, 2025). "Heat map showed the top 50 positively and negatively correlated significant gens with SCARB2 expression in glioma." (PMID 41210942, 2025). "The IHC image confirmed a clear difference in SCARB2 protein levels between high-grade glioma and LGG." (PMID 41210942, 2025). "Combination treatments of EV infection and si-SCARB2 markedly enhanced cell apoptosis in glioma cells compared to monotherapies." (PMID 41210942, 2025). "Building upon these findings, the present study investigates the role of SCARB2, the receptor for Enterovirus A71, its role in immune regulation, and its impact on tumor progression within glioma." (PMID 41210942, 2025). "Our data provided compelling evidence that SCARB2, as EV-A71 receptor in glioma cells, regulates downstream gene expression, offering new insights into the oncolytic virus therapy of tumor progression." (PMID 41210942, 2025). "This research uncovers a previously unidentified mechanism involving SCARB2, which appears to hold a fundamental role in the process of glioma carcinogenesis." (PMID 41210942, 2025). "Here, we systematically identify and characterize critical cellular entry receptors for clinically relevant OVs, particularly focusing on SCARB2 expression and its potential therapeutic implications for oncolytic Enterovirus A71 (EV-A71) therapy in glioma." (PMID 41210942, 2025). "To explore the interactions between tumor and immune system, we utilized the TISIDB database to investigate the distribution of SCARB2 expression across immune and molecular subtypes in glioma." (PMID 41210942, 2025). "Our pan-cancer screening identified the gene SCARB2 as a subject for the focused investigation in glioma." (PMID 41210942, 2025). "To explore potential role of SCARB2 in glioma progression, we analyzed mRNA expression data for SCARB2 across various cancer tissues from 33 cancer types or subtypes in the TCGA database." (PMID 41210942, 2025). "This analysis of an independent dataset supports our initial transcriptomic findings and establishes increased SCARB2 protein abundance in glioma." (PMID 41210942, 2025). "Notably, SCARB2 has also been shown as an EV-A71 receptor to modulate EV-A71 cytolytic activity in glioma." (PMID 41210942, 2025). "SCARB2 significantly was overexpressed in glioma compared to brain tissues." (PMID 41210942, 2025). "Additionally, SCARB2 expression correlated with molecular subtype, immune subtype, and tumor-infiltrating lymphocyte composition in gliomas." (PMID 41210942, 2025). "Elevated SCARB2 protein levels were particularly noted in high-grade gliomas." (PMID 41210942, 2025). "Furthermore, due to the knockdown of SCARB2 in glioma cells, EV-A71 infection further inhibited SCARB2 expression (p < 0.05, p < 0.01)." (PMID 41210942, 2025). "SCARB2 serves as a critical cellular receptor for EV-A71-mediated oncolytic activity in glioma." (PMID 41210942, 2025).
glioma (continued). "Furthermore, SCARB2 and related genes significantly regulated glioma RUNX3/Notch and BMP signaling pathways Overall, our findings reveal SCARB2 as a key receptor for the oncolytic virus EV-A71, suggesting its promise as a therapeutic target in glioma." (PMID 41210942, 2025). "Notably, SCARB2 expression levels were higher in glioma with advanced tumor stages (p < 0.05)." (PMID 41210942, 2025). "We observed that SCARB2 and positively correlated genes influenced the RUNX3/Notch signaling and BMP pathway in glioma." (PMID 41210942, 2025). "Elevated SCARB2 expression in GBM highlights its potential as both a therapeutic target and predictive biomarker for selecting glioma patients responsive to oncolytic EV-A71 therapy." (PMID 41210942, 2025). "To validate the clinical significance of SCARB2 expression in glioma, we utilized the GEPIA2 database to analyze glioma tissue microarrays." (PMID 41210942, 2025). "Activation of the SCARB2/PMAIP1 axis has demonstrated considerable potential in facilitating cell oncolysis and, consequently, eradicating glioma cells." (PMID 37808305, 2023). "Interestingly, SCARB2 expression in WHO grade II and IV gliomas was found to correlate with 1p/19q co-deletion status (p < 0.01, p < 0.001)." (PMID 41210942, 2025). "Furthermore, elevated SCARB2 expression was particularly evident in patients with IDH wildtype status (p < 0.01), except for WHO grade II and III gliomas (p < 0.05, p < 0.01)." (PMID 41210942, 2025). "The absence of SCARB2 leads to a substantial reduction in the capacity for glioma cell growth and migration within in vitro models." (PMID 41210942, 2025). "Additionally, in glioma, excluding GBM, various molecular subtypes showed a significant correlation with levels of SCARB2 expression." (PMID 41210942, 2025). "Interestingly, inconsistent with the IHC protein staining results, patients with glioma with high WHO grade and histological type (GBM) showed a decreased SCARB2 mRNA expression (p < 0.05, p < 0.01, p < 0.001)." (PMID 41210942, 2025).